CXCL9 (C-X-C motif chemokine ligand 9)
Diseases named in the same sentence as CXCL9 in open-access papers (continued):
Sharing a sentence is not in itself a finding about the gene and the disease.
melanoma (continued). "Chemokines CXCL9 and CXCL10 are well described mediators for activated T cell homing in melanoma through their interaction with receptor CXCR333,34." (PMID 35013216, 2022). "For other chemokines, most of them tended to express higher in FGFR Mut melanoma, such as CCL5, CCL19, CXCL9, CXCL10, CXCL11, CXCL13 and CXCL14 (all P > 0.05)." (PMID 36426352, 2022). "We have further built on these findings by demonstrating the role of GPR182 scavenging of CXCL9 and CXCL10 by LECs in the TME of murine melanoma, implicating lymphatic GPR182 as a potential therapeutic target in cancer immunotherapy." (PMID 35013216, 2022). "A six-gene IFN-γ signature (including IDO1, CXCL10, CXCL9, HLA-DRA, STAT1, and IFNG) was identified in a melanoma cohort of the KEYNOTE-001 study to predict response to pembrolizumab." (PMID 35222540, 2022). "In a mouse model of spontaneous melanoma, both DTIC and TMZ have been shown to induce the secretion of chemokines such as CCL5, CXCL9, CXCL10 and CXCL11 by melanoma cells." (PMID 34712615, 2021). "The myPath Melanoma Test utilizes the expression of 14 signature genes, including PRAME, CXCL9, CXCL10, S100A7, S100A8, and S100A9, and nine reference genes to distinguish BN from CMM." (PMID 35008167, 2021). "In melanoma, NK cells are recruited by the inflammatory chemokines CCL5 and CXCL9-11, expressed within the TME, by the engagement of the cognate receptors CCR5 and CXCR3, respectively." (PMID 34712615, 2021). "As for anti-PD-1 blockade, the IFN-γ gene signature (IDO1, CXCL10, CXCL9, HLA-DRA, STAT1, and IFNG) predicts the response to anti-PD-1 therapy in multiple tumors, including melanoma." (PMID 34439264, 2021). "C1QB, CXCL9, CXCL10, DFNA5 (GSDME), FCGR1B, and PRAME were increased in melanoma, and SCGB1D2 was decreased in melanoma, compared to dysplastic nevi or nevi that progressed to melanoma." (PMID 35008167, 2021). "The chemokines that signal through CXCR3, including CXCL9 and CXCL10, have been suggested to promote T-cell infiltration and activation in melanoma and other solid tumors." (PMID 34203869, 2021). "CXCL9, CXCL10, and CXCL12 are important chemotactic factors in the TME, which are able to recruit T cells and increase inflammation in tumors such as melanoma and lung adenocarcinoma." (PMID 34497764, 2021). "Levels of CXCL9 and CXCL10 were also correlated with the presence of tumor-infiltrating T cells in melanoma patients and migration assays confirmed that these chemokines were critical for T-cell influx." (PMID 34203869, 2021). "High levels of CXCL9 and CXCL10 expression in lymph nodes can promote melanoma cell metastasis through the CXCR3 signaling." (PMID 33407095, 2021). "Particularly, CXCL9 and CXCL10 expression in the lymph nodes is reported to promote CXCR3-mediated metastasis of melanoma cells." (PMID 33195424, 2020). "In the KEYNOTE-001 study, six gene signatures of INFG-related genes (IDO1, HLA-DRA, STAT1, CXCL9, IFNG and CXCL10) were previously developed in melanoma patients." (PMID 32107458, 2020). "An additional study reports a significant expression change of six chemokines (namely, CCL2, CCL3, CCL4, CCL5, CXCL9, and CXCL10) related to the lymphocyte infiltration in the melanoma tissue." (PMID 33302400, 2020). "For example, Sitagliptin treatment improves anti-tumour responses via enhanced CCL11-mediated eosinophil migration in hepatocellular carcinoma mouse models, and promotes CXCL9- and CXCL10-mediated dendritic cell trafficking to melanoma tumours." (PMID 33143089, 2020). "In another report, intratumoral injection of IFN-b also increased CD8+ TILs in melanoma by the induction of M1 macrophage-related chemokines (CXCL9, CXCL10, CXCL11), leading to enhancement of the anti-tumor effects of anti-PD1 Abs for melanoma in vivo." (PMID 32707850, 2020). "Logistic regression revealed that the key genes responsible for these results were CXCL9 and SPP1 for melanoma and IL6 and CXCL13 for LSCC." (PMID 32383556, 2020).
melanoma (continued). "Functional studies revealed that blockade of CXCL9 and CXCL10, or their receptor CXCR3, impairs recruitment of adoptively transferred T cells into melanoma tumors." (PMID 30873179, 2019). "One of the earliest studies to link chemokine expression in human melanoma to CD8+ T cell infiltration used gene expression arrays to identify CCL2-5 and CXCL9 as preferentially expressed in T cell rich patients' tumors." (PMID 30899263, 2019). "In a therapeutic setting for melanoma, adjuvant IFN-α therapy of melanomas is known to upregulate CXCL10 production while CXCL9 and CXCL10 were induced in melanomas by chemotherapy agents such as cisplatin." (PMID 30320116, 2018). "In the case of B16F10 melanoma cells, the chemoattractants produced by PMF are the Cxcr3 ligands, Cxcl9 and 10, and most likely, SSeCKS regulates production of Cxcl9/10 in PMF through its control of PKC, PKA and PI3K/AKT signaling." (PMID 29050279, 2017). "The CD103+ DCs elevated CXCL9 and CXCL10 in order to further attract T cells to infiltrate the tumor, and deletion of CCL4 in the melanoma cells abrogated T cell infiltration." (PMID 29109732, 2017). "For instance, CCL5 and CXCL9 and CXCL10 contributed to the recruitment of CD8 T cells in a mouse model of spontaneous melanoma." (PMID 27096098, 2016). "Previously, we found that melanoma-activated TIL induced MSCs to produce a wide variety of chemokines including the Th1 chemokines CCL5, CXCL9, CXCL10 and CXCL11 and the Th1 cytokine IL-125." (PMID 27211104, 2016). "The CXCR3 ligands, CXCL9 and CXCL10, within the LNs of host mice have facilitated metastasis of murine melanoma cells through CXCR3." (PMID 25798946, 2015). "On the one hand, the chemokine CXCL9 has been described as a key mediator in homing and metastasis, as confirmed by the fact that expression of CXCL9 and CXCL10 in the lymph nodes facilitates melanoma cell metastasis in a murine model." (PMID 21179030, 2011). "We observed that tumour endothelial cells (ECs) secrete high levels of CXCL9 in all, and CXCL10 in most melanoma metastases." (PMID 21179030, 2011). "In addition, we found that IκBζ simultaneously repressed several chemokines such as Cxcl9, Cxcl10, and Ccl5 in D4M-3A, YUMM1.7, and B16-F10 melanoma in vivo." (PMID 40562773, 2025). "Importantly, CXCL9+ and IL‐12p40+ cDC1s were not only found in MCA205 LA‐OVA tumours but could also be detected in other tumour models (MC38, YUMMM1.7, COX‐deficient BrafV600E 5555 melanoma, B16‐F10), arguing that they are a common feature of murine transplantable tumours." (PMID 40745918, 2025). "Upregulations of Cxcl9, Cxcl10, Cxcl11, Ccl5, Tap1, CD74, Irf1, Icam1, CD40, Fas and PD-L1 were detected after Mi-2β silencing and the anti-PD-1 treatment in BRafV600E/Ptennull melanomas." (PMID 38461299, 2024). "Notably, human A375 melanoma cells produced a similar base level of CXCL10 and CXCL9 (about 200 pg/ml) but in response to IFN-γ, it showed about a 6-fold increase in CXCL10 production, with no increase in CXCL9 production." (PMID 39474427, 2024). "There was a negative correlation tendency between Mi-2β and Cxcl9 and Cxcl10 at the mRNA level in melanomas in TCGA." (PMID 38461299, 2024). "CXCL9 and CXCL10 genes also play important roles in tumors, such as melanoma and colorectal cancer." (PMID 38448514, 2024). "Moreover, melanoma patients who express low levels of CXCL9 or CXCL10 (either blood or tumor site) are poor responders to ICT, and those with high levels of CXCL9 or CXCL10 respond more favorably." (PMID 39474427, 2024). "Clinically, it has been shown that elevated pre-treatment CXCL9 and CXCL10 levels correlate with the response to anti-PD-L 1 therapy in patients with non-small cell lung cancer, and CXCL9 and CXCL10 increase in the first months of treatment in melanoma patients responding to PD-1 inhibitor therapy." (PMID 37569757, 2023).
melanoma (continued). "Interestingly, a previous study detected elevated plasma CXCL9 and CXCL10 levels in mice that responded to ICI therapy, and similar results were recorded in patients with melanoma." (PMID 38133557, 2023). "Similarly, we found an increase in CXCL9 and CXCL10 in the first months of treatment with PD-1 inhibitors in responders with melanoma." (PMID 37569757, 2023). "injection, NPTyr-C9AP can cross physiological barriers and co–express abundant CXCL9 and αPD-L1 specifically in melanoma cells but not in normal cells." (PMID 37031188, 2023). "Correspondingly, the concentrations of CXCL9 and αPD-L1 proteins in the culture supernatants of NPTyr-C9AP-transfected B16-F10 cells reached 0.47 and 2.19 ng ml−1, which were much higher than that of other cells due to the melanoma specificity of NPTyr-C9AP." (PMID 37031188, 2023). "Furthermore, strong evidence from imaging mass cytometry in human melanoma, suggest that CXCL9 is a major chemoattractant for cytotoxic CD8+ T cells, and CXCL9 and CXCL10 expressing cells accumulating in areas of active anti-tumor activity." (PMID 36845555, 2023). "Higher levels of CXCL9, CXCL10, and CXCL11 were also detected in melanoma patients’ tumors following treatment with ipilimumab, an antagonistic antibody against cytotoxic T-lymphocyte-associated protein 4 (CTLA4), another inhibitory receptor expressed by T cells." (PMID 33603130, 2022). "In vitro, small extracellular vesicles from melanoma cells overexpressing wild-type nSMase2 enhance the expression of IL12, CXCL9, and CCL19 in bone marrow-derived dendritic cells, suggesting that melanoma nSMase2 triggers Th1 polarization at the earliest stages of the immune response." (PMID 35965565, 2022). "Thus, in vitro experiments have shown that IFN-β treatment induced CXCL10 expression of melanoma cells and DCs stimulated with IFNα/IFN-β produced significant amounts of CXCL9 and CXCL10." (PMID 35626062, 2022). "Four of these Top HRLs are recognized by 2 of the Top HRs and represent ligand-receptor pairs that have been previously identified as crucial mediators of T and B cell trafficking in melanoma: CXCL10 and CXCL9 are ligands for CXCR3; and CCL4 and CCL5 are ligands for CCR5." (PMID 34454518, 2021). "CXCL8, CXCL9, CXCL10, CCL27, and C3AR1 have known immunomodulatory roles in melanoma." (PMID 35008167, 2021). "Indeed, both pre- and post-treatment CXCL9 and CXCL10 expression levels correlate with response to anti-PD-1 treatment in melanoma patients and anti-PD-L1 treatment in urothelial cancer patients." (PMID 34030676, 2021). "Effector T cells from adoptive T cell transfer fail to traffic to a non-T cell-inflamed melanoma model due to lack of CXCL-9/10 production." (PMID 34620867, 2021). "Moreover, IFNγ signatures (CXCL10, CXCL9, IDO1, IFNG, and STAT1) and myeloid lineage phenotypic and functional markers (CD14, CD163, CD33, and CD68) were also significantly increased in melanoma patients with high ETV7." (PMID 33424867, 2020). "Notably, gene expression sequences from melanoma biopsies also revealed a positive correlation between CCL5, CXCL2, CXCL9, and CXCL10 and clinical benefit in a phase II trial of a MAGE-A3 vaccine." (PMID 30899263, 2019). "For example, in melanoma, the lack of CCR5 ligands (CCL3, CCL4, CCL5) and CXCR3 ligands (CXCL9 and CXCL10) has been associated with limited infiltration of antigen-specific T cells." (PMID 30873179, 2019). "Moreover, therapies such as dacarbazine and temozolomide induce the CD8+ T cell chemoattractants CCL5, CXCL9, and CXCL10 in human melanoma cell lines." (PMID 30899263, 2019). "Furthermore, IFN-γ treatment induced chemokines CXCL9 and CXCL10 in melanoma potentially facilitating T cell infiltration." (PMID 30899263, 2019). "The direct contribution of primary melanoma cells to the secretion of CXCL9/10/11 is not clear although metastatic melanoma cells in vitro can produce CXCL9/10/11 in response to IFN." (PMID 30320116, 2018).
melanoma (continued). "Lipopolysaccharides can stimulate normal human melanocytes to produce IL-1β, TNFα, IL-6, IL-8, CCL2, CCl3, and CCL5, and chemotherapy of melanoma-bearing mice results in enhanced expression of CCL5 and the CXCR3 ligands CXCL9, CXCL10, and CXCl11 by tumor cells." (PMID 22745913, 2012). "None of the treatments with 0–400 ng ml−1 CXCL9 or CXCL10 influenced cell death or cell proliferation in melanoma cells (data not shown)." (PMID 21179030, 2011). "In this study, we observed that the chemokine CXCL9 is highly secreted by tumour endothelial cells (TuECs) in melanoma metastases and that CXCR3 receptors are expressed on all isolated melanoma cells, regardless the tissue from which the metastasis was surgically removed." (PMID 21179030, 2011). "Transmigration of Melanoma-7 cells (Cell Tracker-568) through monolayers with 15 or 25% CXCL9-transfected, 18% mock-transfected or non-transfected HUVECs (transfection efficiency defined by FACS analysis (EGFP-positive cells)) was allowed for 8 h." (PMID 21179030, 2011). "In this report, we show for the first time that high concentrations of the soluble chemokine CXCL9 preferentially promote chemokinesis and the chemorepulsive migration of human melanoma cells rather than the movement towards the chemogradient." (PMID 21179030, 2011). "In mouse melanoma models, eosinophil recruitment induced by Tregs depletion or by IL-33 treatment mediated melanoma regression through production of CD8+ T cell attracting chemokines (i.e., CXCL9, CCL10 and CCL5) by promoting tumor-reactive CD8+ T cell responses." (PMID 40050933, 2025). "Thus, we hypothesized that IκBζ might repress CXCL9, CXCL10, and CCL5 expression through the interaction with EZH2 and/or HDAC3 in melanoma." (PMID 40562773, 2025). "Interestingly, the CXCL9/CXCL10 secretion increase was stronger after coadministration of GUA and MAPKi, suggesting a possible addictive interaction between these 2 compounds in regulating melanoma T helper 1 chemokine secretion." (PMID 39867570, 2025). "Moreover, DNA-methylation inhibition increased CXCL9/CXCL10 secretion, overexpression of major histocompatibility complex class I/II antigens and components of the antigen-processing machinery, thus suggesting the augmentation of melanoma immunogenicity." (PMID 39867570, 2025). "At least two-fold upregulation of CXCL9, CXCL10, and CXCL11 was observed in all cancer types including melanoma (n = 77), breast cancer (n = 40), brain cancer (n = 198), and lung cancer when comparing samples with high to low MOTIscores, with significance for melanoma and breast cancer." (PMID 41463470, 2025). "In a phase I study of atezolizumab for patients with advanced melanoma, elevated expression of IFN-γ as well as IFN-γ-inducible genes (for example, indoleamine 2,3 dioxygenase 1 [IDO1] and C-x-C motif chemokine ligand 9 [CXCL9]) in pre-treatment tumours were demonstrated in responding patients." (PMID 39530091, 2024). "After separately proving the ability of NPTyr-C9AP to enhance T-cell recruitment and activation by expressing CXCL9 and αPD-L1, we designed a transwell migration and cytotoxicity assay to detect the synergistic effects of NPTyr-C9AP on recruiting and activating T cells to kill melanoma cells." (PMID 37031188, 2023). "Macrophage-derived CXCL9 and CXL10 have been recognized as markers for an improved response to immunotherapy in melanoma patients, and are required for the efficacy of immunotherapy in murine syngeneic models of MC38 (colon cancer), AT-3, E0771 (breast cancer), and B16F10 (melanoma) models." (PMID 38140561, 2023). "A similar result was obtained in urothelial, melanoma, and non-small cell lung carcinoma in which IFN-γ signaling-related genes, including IFNG, CD274, LAG3, and CXCL9, could well predict about who could benefit from the immunotherapy via anti-PD-L1/PD-1 antibody." (PMID 37637034, 2023).
melanoma (continued). "Immune-profiling and cell depletion experiments revealed that melanoma cell-derived Activin-A reduces the dependence on suppressive CD4+ T cells to escape immune surveillance, correlating with the diminished secretion of specific chemokines such as CXCL9 and CXCL10." (PMID 35580932, 2022). "They demonstrated that inhibition of tumor acidosis by adenylyl cyclase inhibitor MDL-12 induces NOS, CXCL9, CXCL11 and TNF-α-expressing proinflammatory TAMs that phenotypically resemble classical M1 macrophages, leading to suppression of tumor growth in B16 mouse melanoma." (PMID 32707850, 2020). "The CXCL9, CXCL10, and CXCL11/CXCR3 axis was generally considered to have antiangiogenic effects on endothelial cells and has been reported as effective tumor angiogenesis inhibitors in some in vivo tumor models, including pancreatic cancer, breast cancer, lung cancer, and melanoma." (PMID 32685487, 2020). "The expression of CXCL9 was induced only by DAC treatment in 20% (2/10) chemokine-negative melanoma cells, while it was up-regulated (FC ≥2) by treatment with guadecitabine and DAC in 25% (1/4) and 75% (3/4) chemokine-positive melanoma cells, respectively, compared to 0% in AZA-treated cells." (PMID 30581389, 2018). "Thus, our results support a model in which IκBζ-mediated recruitment of EZH2 and HDAC3 represses Cxcl10, Cxcl9, and Ccl5 in melanoma, contributing to the observed lack of T-cell infiltration and immunotherapy resistance in the α-PD-1-treated, IκBζ-expressing melanoma mouse models." (PMID 40562773, 2025). "Also, in another scientific study that analyzed plasma samples from 28 patients with advanced melanoma who were treated with pembrolizumab and nivolumab plus ipilimumab, responders (n = 18) had a greater quantity of CXCL9 and CXCL10 compared to non-responders (n = 10)." (PMID 39273452, 2024). "Although the chemokines CXCL9, CXCL10 and CXCL11 were reported to have an angiostatic effect when expressed by melanoma cells, our study suggests that the chemokine CXCL9 may promote additional metastasis, when it is expressed in TuECs, by means of increasing transendothelial and melanoma migration." (PMID 21179030, 2011). "Moreover, a cohort study in melanoma tissues revealed negative associations between intratumoral members of the genera Algibacter and Epilithonimonas and CD8+ T cell infiltration, while the Algibacter genus was also negatively correlated with overexpression of the chemokines CXCL9, CXCL10 and CCL5." (PMID 39120310, 2024). "Intriguingly, while CXCL2 was expressed by fibroblasts from all skin cancer types, melanoma-derived CAFs expressed high levels of CXCL1-3, 5, 6 and 8 and IL1B as well as IL6, whereas the expression of CXCL9-11 and 13 was high in non-melanoma CAFs." (PMID 39516494, 2024). "CXCL9, CXCL10, PD-L1, CD86, IL-10, TREM2, GPNMB, IL-4l1 and FOLR2 markers showed widespread expression by most melanoma TAMs, with no definition of a particular macrophage subset, and regardless of whether the tumor was metastasizing or not." (PMID 40406129, 2025). "We show that Activin-A secretion by melanoma cells inhibits adaptive antitumor immunity irrespective of BRAF status by inhibiting CD8+ T cell infiltration indirectly and even independently of CD4 T cells, at least in part by attenuating the production of CXCL9/10 by myeloid cells." (PMID 35580932, 2022).